IL33 (interleukin 33)
Diseases named in the same sentence as IL33 in open-access papers (continued):
Sharing a sentence is not in itself a finding about the gene and the disease.
nasal polyps (36 papers, 2012 to 2025). "We aimed to study tissue IL-33 in CRSwNP, using an enzyme-linked immunosorbent assay (ELISA) to investigate its involvement as a novel potential regulator of innate immunity, and biomarker of disease severity, in chronic rhinosinusitis with nasal polyps." (PMID 38137606, 2023). "Mast cells (MCs) are involved in type 2 inflammation in chronic rhinosinusitis with nasal polyps (CRSwNP), which depends on interleukin (IL)‐33 stimulation." (PMID 40131162, 2025). "Stevens and Kato reported a 100-fold increase in ILC2s in nasal polyps, whereas others have observed context-dependent activation, with epithelial-derived IL-33 being essential in early inflammation but less so in chronic stages." (PMID 40672703, 2025). "Genetic research has drawn connections between IL-33 levels and the occurrence of nasal polyps in CRSwNP." (PMID 38680486, 2024). "Novel biologic agents blocking the production or action of such cytokines, including, for instance, IL-5, IL-5Rα, IL-33 and immunoglobulin (Ig)E, have been developed and examined for treatment of chronic rhinosinusitis-related nasal polyps." (PMID 37375083, 2023). "Further studies will better clarify the role of IL-33 as a novel potential regulator of innate immunity and a biomarker of disease severity in chronic rhinosinusitis with nasal polyps." (PMID 38137606, 2023). "Type 2 inflammatory cytokines such as IL-4, IL-13, IL-8, and IL-33 in CRSwNP patients enhanced expression of MUC5AC in nasal polyp-derived epithelial cells." (PMID 36506304, 2022). "S. aureus binding to TLR 2 directly induces the release of epithelial cell-derived cytokines and promotes the expression of TSLP, IL-5, IL-13, and IL-33 in nasal polyp tissue." (PMID 35878202, 2022). "The expression of IL-5, POSTN and IL-33 mRNA was determined in sinonasal mucosal samples and in nasal polyp tissue by real-time PCR." (PMID 35752781, 2022). "Interleukin-33 (IL-33) is a an inducer of mast cell activation and innate type 2 immunity and is present in increased levels in the nasal polyp tissues of patients with N-ERD." (PMID 34305932, 2021). "The neurohormonal mediators interleukin-33 (IL-33) and Substance P (SP) stimulate mast cells and have been suggested in the pathophysiology of nasal polyposis." (PMID 34680251, 2021). "IL-33 is also involved in tissue remodeling: concentration of matrix metalloproteinase (MMP)-2 and -9 is positively correlated with IL-33 mRNA levels in nasal polyps, and it contributes to edema formation." (PMID 35008843, 2021). "Interleukin (IL)-10, IL-25, IL-33, and thymic stromal lymphopoietin (TSLP) levels were determined using the enzyme-linked immunosorbent assay (ELISA) in nasal polyp tissues." (PMID 32294933, 2020). "This study aimed to measure the expressions of IL-17RB, ST2 and TSLPR, receptor of IL-25, IL-33, and TSLP respectively, on myeloid DCs in nasal polyps (NP) and evaluate their association with local Th2 inflammation and disease severity in patients with NP." (PMID 30519393, 2018). "In humans, IL-33 expression is highly upregulated in AERD patient nasal polyps, AR patient nasal secretions, and asthmatic airways (with severe asthmatics demonstrating the highest expression)." (PMID 28959799, 2017). "So far, a similar level of induction of IL-6, IL-8, and IL-33 in the epithelia of healthy controls and nasal polyposis patients in responses to different bacterial TLR agonists was shown with the viral analogue poly(I:C) (TLR-3 agonist)." (PMID 27050744, 2016). "In this study an enrichment of IL-33 responsive CRTH2+ ILC2s is shown in nasal polyps providing a source of TH2 cytokines." (PMID 25932636, 2015). "IL-33 has recently come into focus of research in CRS, as its receptor ST2 has been shown to be elevated in CRSwNP and IL-33 responsive innate lymphoid cells were found in nasal polyps." (PMID 25932636, 2015).
nasal polyps (continued). "Recent data have identified human IL-33–responsive ILC populations that are present in increased numbers in nasal polyps of patients with chronic rhinosinusitis." (PMID 22738676, 2012). "Notably, the number of IL-33-responding ILCs was also increased in the nasal polyps of patients with rhinosinusitis." (PMID 38137606, 2023). "Pathogenesis of nasal polyps has been extensively studied; epithelial derived innate cytokines, including IL-33, promote Th2 responses via the development of innate lymphoid cells to ensure the persistence of disease, even when the mucosa is either treated medically or removed." (PMID 38137606, 2023). "If we excluded all patients with nasal polyps, severe asthmatics (n = 12) still had significantly higher expression in IL-33-axis cytokines, Th2 cytokines, ILC2 cells, yearly decline of pulmonary functions, and post-operative improvements in ACT scores than those in non-severe asthmatics (n = 11)." (PMID 28199345, 2017). "Moreover, we see only the increased TSLP induction and no increased induction of the other Th2-skewing mediators IL-25 and IL-33 in nasal polyposis epithelium." (PMID 27050744, 2016). "Both IL-33 and TSLP are abundantly present in nasal polyp tissues and are influential in the inflammatory pathways as demonstrated in non-human studies." (PMID 38680486, 2024). "The CRSwNP mainly showed Th2 cell inflammation, mainly involving the effects of IL-4, IL-5, and IL-13, accompanied by changes in IL-25, IL-33, TSLP and IgE levels, with eosinophil infiltration and nasal polyps phenomenon." (PMID 36506304, 2022). "In nasal polyp tissue, S. aureus can directly induce the release of the epithelial cell-derived cytokines TSLP and IL-33 by binding to TLR 2, thereby potentially propagating the expression of type 2 cytokines IL-5 and IL-13 in nasal polyp tissue." (PMID 35878202, 2022). "Several studies have reported upregulated expression of IL-33 and its receptor ST2 in nasal polyps at both the mRNA and the protein levels." (PMID 35008843, 2021). "In epithelial cells of nasal polyps (eosinophil-rich areas), TSLP, IL-25, and IL-33 were higher than in those of uncinate process tissues (eosinophil-poor areas)." (PMID 32085629, 2020). "Although Alternaria and HDM induced IL-33 and TSLP production from nasal epithelial cells, the concentration of these two chemical mediators in cultured media was much lower than that of nasal polyp tissues." (PMID 32294933, 2020). "This conforms to findings that the mRNA and protein levels of IL-33 and ST2 are significantly higher in nasal polyps of CRSwNP and ECRS." (PMID 29987222, 2018). "Nasal polyps from patients with CRS have elevated levels of CysLTs, IL-33, TSLP, and IL-4 and multiple groups have shown that ILC2s are enriched in nasal polyps, especially eosinophilic polyps, compared to control tissue." (PMID 28959799, 2017). "In this manuscript we explore the reactivity of epithelial cells isolated from nasal polyps and healthy controls to a broad range of TLR agonists in their ability to induce the expression and production of TSLP, IL-25, and IL-33." (PMID 27050744, 2016). "Subsequently, a role for TSLP in activation of ILC2 was demonstrated as purified human peripheral blood and nasal polyp ILC2 cultured with TSLP and IL-33 displayed enhanced IL-4, IL-5, and IL-13 production above IL-33 alone." (PMID 24876829, 2013). "Further work has shown that ILC2 from nasal polyps produce IL-13 in a GATA3-dependent manner after culture with IL-2, IL-33 and TSLP." (PMID 24876829, 2013). "Contrary to our studies, PM 10 treatment did not affect cell viability in nasal polyp-derived fibroblasts (NPDFs) while increase the IL-33/ST2 pathway-mediated immune response." (PMID 38130933, 2023).
nasal polyps (continued). "Our data are consistent with recent work showing that JAGGED‐1 elicits Th2 responses, thus stimulating the airway inflammation, and in nasal polyps epithelial cells the JAGGED‐1 mediated activation of Notch signaling increases nuclear and cytoplasmic levels of IL‐33." (PMID 36029197, 2022). "In this same study, genetic variation in IL1RL1 (rs1420101), which is the receptor for IL-33, failed to associate with CRS and nasal polyps." (PMID 36419128, 2022). "The positive feedback loop between IL-33 and TSLP and their receptors might facilitate the Th2-skewed inflammation in eosinophilic chronic rhinosinusitis with nasal polyps." (PMID 30123216, 2018). "The induction levels for IL-33 are remarkably similar and range between 2.0 ± 0.2 (p < 0.05) and 4.1 ± 2.35 (p < 0.05) fold for most TLR agonists (flagellin, PAM, CpG, and PGN) acting on epithelial cells isolated from healthy nasal mucosa or nasal polyps." (PMID 27050744, 2016). "However, the TLR7/8 agonist R848 triggers the induction of IL-33 in healthy epithelium only (23.2 ± 6.17, p < 0.05) and not nasal polyposis epithelium (1.57 ± 0.38), despite the IL-6 and IL-8 induction levels being similar between those two groups." (PMID 27050744, 2016). "ST2 was over-expressed in ILCs from CRSwNP tissues compared with chronic rhinosinusitis without nasal polyp (CRSsNP), and ST2-positive ILCs were a source of IL-13 in response to IL-33." (PMID 38137606, 2023). "The aim of the study was to determine the expression of IL-5, POSTN and IL-33, at the gene and protein levels, in eosinophilic CRS with nasal polyps (CRSwNP) and without nasal polyps (CRSsNP), and to correlate this expression with clinical severity." (PMID 35752781, 2022). "However, some treatments, such as anti-IL-33, did not significantly reduce the Sino-Nasal Outcome Test-22 (SNOT-22) score, nasal polyp score (NPS), or eosinophil count, indicating insufficient therapeutic efficacy." (PMID 40292285, 2025).
parasitic infections (35 papers, 2014 to 2026). "In contrast, mice treated with IL-33 displayed reduced body weight loss, clinical score and survived up to day 20 post-infection when they were euthanised due to development of hyperparasitemia (up to 40% parasitemia)." (PMID 25659095, 2015). "To understand the mechanisms limiting the impact of IL-33 on inducing trTregs during T. cruzi infection, we focused on molecules known to counteract IL-33’s biological effects, potentially activated by this parasitic infection." (PMID 39883714, 2025). "RAW 264.7 macrophages were subjected to parasite infection for various periods and IL-33 level was determined by ELISA." (PMID 38750790, 2024). "IL-33 plays a crucial role in activating MCs and in enhancing the immune response against mechanical injury and bacterial and parasitic infections." (PMID 39591475, 2024). "In parasitic infection, IL-33 released by epithelial cells in the intestine induces a type 2 immune response which results in parasite ejection." (PMID 39514278, 2024). "In contrast to other members of the IL-1 family (such as IL-1 and IL-18, which primarily promote type 1 immune responses), IL-33 generally promotes type 2 immune responses and is involved in allergic disorders, parasitic infections, and inflammation." (PMID 37686309, 2023). "ILC2 can secrete IL-13 to promote mucus secretion by goblet cells, thus playing a crucial role in parasitic infections; this process is reliant on IL-33." (PMID 37686309, 2023). "In this review, we explore IL-33/ST2 signaling of the innate immune system's response and provide insight into its role during parasitic infections caused by Toxoplasma, Plasmodium, Leishmania, and helminths." (PMID 32363166, 2020). "Despite IL-33 being one of the earliest responders during infection involved in priming the host immune system toward a Th2 response, its involvement in many parasitic diseases is widely unexplored." (PMID 32363166, 2020). "Not only does IL-33 play a role in parasitic disease, but implications for IL-33 have also been found in the context of cancer." (PMID 32363166, 2020). "Interleukin-33 (IL-33) has been described as a potent promoter of type II immunity that triggers an innate immune response to allergic inflammation and parasitic infections." (PMID 33308251, 2020). "The involvement of IL-33 in Treg regulation should be further explored in the context of cancer as well as parasitic diseases, as IL-33 immunotherapy is presenting itself as a potential therapeutic option." (PMID 32363166, 2020). "As one of the earliest responses to damage or infection, IL-33 finds itself within a unique niche in host immunity to parasitic infection, where it plays a role in priming and modulating the adaptive immune response." (PMID 32363166, 2020). "Within this review, we will be focusing on IL-33/ST2 signaling within the context specifically of parasitic infection." (PMID 32363166, 2020). "Application of IL-33 modulates the Th1-Th2 balance and promotes Th2 cells only when given in early phase of the immune response during parasitic infection." (PMID 30498495, 2018). "Interleukin-33 (IL-33) plays multiple roles in tissue homeostasis, prevention of parasitic infection, and induction of allergic inflammation." (PMID 30233590, 2018). "IL-33-treated mice, though consistently showed significant reduction in parasitemia at the early stage of infection (day 5–7) compared to untreated mice, were unable to clear the parasite and eventually died at later stage from hyperparasitemia." (PMID 25659095, 2015). "IL-33 can function as a proinflammatory cytokine inducing Th2 type of immune response being involved with the defense against parasitic infections of the gastrointestinal tract." (PMID 24701033, 2014). "Alarmin cytokines including IL-25, IL-33, and thymic stromal lymphopoietin (TSLP) function as danger signals to trigger host immunity in response to tissue injury caused by pathogenic factors such as parasitic infections." (PMID 39559705, 2024).
parasitic infections (continued). "Furthermore, we have emphasized the role of IL-33 in gastrointestinal cancer and parasitic infections, giving novel prospective therapeutic utility in the future application of IL-33." (PMID 37686309, 2023). "IL-33 has a substantial impact on inflammatory autoimmune disorders, gastrointestinal cancer, and parasitic infections, and regulating its signaling pathways may aid in the treatment of various disorders." (PMID 37686309, 2023). "In addition to other members of the IL-1 family, IL-33 is a key cytokine in parasite infections and drives the activation of ILC2 and Th2 cells and the induction of type 2 cytokines (in particular, IL-13), which promote intestinal nematode expulsion or control Toxoplasma gondii encephalitis." (PMID 41087719, 2025). "When it comes to innate immunity, IL-33 potently stimulates innate lymphoid cells type 2 (ILC2s), facilitating their proliferation and secretion of type 3 cytokines such as IL-5 and IL-13, which are essential in responses to parasitic infections and allergic inflammation." (PMID 41284319, 2025). "Therefore, the IL-33/ST2 pathway may play an important role in the defense against this parasitic disease." (PMID 38787044, 2024). "Because of its dual properties, IL-33 could serve as an immune-modulatory target for the early or prophylactic therapies against parasitic infections, where controlled intervention could possibly allow for a more dictated adaptive immune response by the physician." (PMID 32363166, 2020). "Research investigating IL-33/ST2's role in parasitic infection shows that its modulation may demonstrate a viable treatment strategy, though due to the varying nature in IL-33/ST2 signaling in the host immune response, there is a need for further research on the topic." (PMID 32363166, 2020). "During type 2 polarized immune responses e.g. induced by parasitic infections or atopic diseases, CCL1 has been shown to be primarily produced by mast cells and ILC2s most likely by stimulation via alarmins, such as IL-33." (PMID 33613532, 2020). "The function of tuft cells was rather unclear until three studies recently demonstrated that tuft cells initiated type II immune response by secreting the cytokine IL25, IL33, and TSLP (thymic stromal lymphopoietin) following parasite infections in the murine intestine." (PMID 29163195, 2017). "In vivo imaging using luciferase-expressing PbA confirmed that the parasite biomass was significantly reduced in IL-33-treated mice indicating that the reduction in blood parasitemia was not due to an increase of parasite sequestration in the peripheric organs." (PMID 25659095, 2015). "While the IL-33/ST2 signaling axis has been researched in the context of many systems and diseases, the roles of such findings in the context of parasitic disease have not been exhaustively compiled." (PMID 32363166, 2020).